LINC02038 (long independently transcribed non-coding RNA 2038)
Gene: Long non-coding RNA gene on chromosome 3 (193,818,833 to 193,844,024, reverse strand). Ensembl gene ENSG00000229155.
Diseases named in the same sentence as LINC02038 in open-access papers:
LINC02038 is named in the same sentence as 2 diseases in open-access papers, as found by Europe PMC text mining. Sharing a sentence is not in itself a finding about the gene and the disease. The quoted sentences say what the papers report.
tumor (1 paper, 2023). "In the high-risk score group, up-regulated PXDNL and LINC02038 promote the formation of immunosuppressive microenvironment and promote tumor progression by affecting NK cells and CTL." (PMID 36869083, 2023). "Among TME-related prognostic signature, KLRB1, SCL27A2, PXDNL, LINC02038, IGHV1-12, IGKV1OR2-108 were directly related to tumor immunity to a certain extent, reflecting the characteristics of natural killer cells, natural killer T cells and other immune cells." (PMID 36869083, 2023).
LINC02038 also shares sentences with these, for which no sentence is quoted: cancer (1 paper).